HNRNPUL2-BSCL2 (HNRNPUL2-BSCL2 readthrough (NMD candidate))
Gene: Protein-coding gene on chromosome 11 (62,690,275 to 62,727,384, reverse strand). Ensembl gene ENSG00000234857.
Genetic constraint (gnomAD): Missense variants: 900 observed, 897.06 expected, observed/expected ratio (o/e) 1, 90% interval 0.95 to 1.06. Synonymous variants: 441 observed, 350.62 expected, observed/expected ratio (o/e) 1.26, 90% interval 1.16 to 1.36.